ERP29 (endoplasmic reticulum protein 29)
Description:
Does not seem to be a disulfide isomerase. Plays an important role in the processing of secretory proteins within the endoplasmic reticulum (ER), possibly by participating in the folding of proteins in the ER.
Synonyms: ERp28; ERp31; C12orf8; PDI-DB; PDIA9; HEL-S-107
Tractability: Antibody: UniProt predicts a signal peptide or a membrane-spanning region. PROTAC: ubiquitination databases record sites on it; its protein half-life has been measured.
Gene: Protein-coding gene on chromosome 12 (112,012,815 to 112,025,268, forward strand). Ensembl gene ENSG00000089248.
Subcellular location: Endoplasmic reticulum lumen; Melanosome
Subcellular location (Human Protein Atlas): Microtubules; Nucleoplasm
Gene Ontology:
Molecular function: protein binding; protein disulfide isomerase activity; protein-folding chaperone binding; protein homodimerization activity
Biological process: negative regulation of gene expression; negative regulation of protein secretion; positive regulation of gene expression; positive regulation of MAPK cascade; intracellular protein transport; protein folding; protein unfolding; endoplasmic reticulum to Golgi vesicle-mediated transport; protein secretion; regulation of endoplasmic reticulum stress-induced intrinsic apoptotic signaling pathway; response to hormone
Cellular component: cell surface; endoplasmic reticulum; membrane; endoplasmic reticulum lumen; smooth endoplasmic reticulum; extracellular region; melanosome
Genetic constraint (gnomAD): Loss-of-function variants: 14 observed, 22.76 expected, observed/expected ratio (o/e) 0.62, 90% interval 0.41 to 0.96. The upper end of that interval is the gene's LOEUF score, 0.96, which puts it in group 4 of 6, group 1 being the genes least tolerant of losing a copy. Missense variants: 286 observed, 340.81 expected, observed/expected ratio (o/e) 0.84, 90% interval 0.76 to 0.93. Synonymous variants: 129 observed, 145 expected, observed/expected ratio (o/e) 0.89, 90% interval 0.77 to 1.03.
Homologues: Orthologues: chimpanzee ERP29 (99% identical), macaque ERP29 (98% identical), rabbit ERP29 (93% identical), dog ERP29 (93% identical), guinea pig ERP29 (92% identical), pig ERP29 (90% identical), rat Erp29 (90% identical), mouse Erp29 (89% identical), tropical clawed frog erp29 (58% identical), Drosophila melanogaster wbl (29% identical).
Diseases named in the same sentence as ERP29 in open-access papers:
ERP29 is named in the same sentence as 50 diseases in open-access papers, as found by Europe PMC text mining. Sharing a sentence is not in itself a finding about the gene and the disease. The quoted sentences say what the papers report.
breast carcinoma (24 papers, 2012 to 2023). "Recently, the endoplasmic reticulum (ER) protein 29 (ERp29) has been shown to inversely associate with primary tumor development and function as a tumor suppressor in breast cancer." (PMID 28874138, 2017). "In this study, we investigate the molecular base underlying ERp29-mediated radioresistance in MDA-MB-231 breast cancer cells." (PMID 26420420, 2015). "When injected into nude mice, breast cancer cells overexpressing Erp29 demonstrated delayed tumor formation as compared to control." (PMID 36835266, 2023). "ERp29-transfected human breast cancer MDA-MB-231 cells have been demonstrated to change the morphology into one that is more epithelial and to stimulate growth in clusters, while control cells retained their predilection for more scattered growth in vitro." (PMID 36835266, 2023). "In breast cancer, low expression of miR-205-5p leads to upregulation of ERp29 and decreased sensitivity of cancer cells to gemcitabine." (PMID 35538494, 2022). "Among many, angiomotin (AMOT) and Endoplasmic Reticulum Protein 29 (ERp29) are the direct targets for miR-205 in breast cancer and miR-205 binds to the 3′ UTR site of both genes." (PMID 32854238, 2020). "For example, miR-205 was seen to reduce gemcitabine resistance by targeting endoplasmic reticulum protein 29 (ERp29) levels in breast cancer." (PMID 33375067, 2020). "Recently, abnormal expression of ERp29 was found in many kinds of malignant tumors, such as basal cell carcinoma, lung cancer, breast cancer and colorectal cancer." (PMID 29108263, 2017). "Other findings indicated that ERp29 expression correlated with tumor growth rate and knockdown of ERp29 by shRNA in non-invasive MCF-7 breast cancer cells reduced tumor formation." (PMID 29108263, 2017). "We here reported that ERp29 expression in the triple negative MDA-MB-231 breast cancer cells significantly increased cell survival against ionizing radiation." (PMID 26420420, 2015). "Previous studies have demonstrated a significant role of ERp29 in the resistance to DOX in breast cancer cells." (PMID 26420420, 2015). "Taken together, the ERp29-induced MGMT is a key molecule promoting ERp29-mediated radioresistance in breast cancer cells." (PMID 26420420, 2015). "Our previous studies have demonstrated a significant role of ERp29 in breast cancer cell survival against doxorubicin-induced genotoxic stress." (PMID 26420420, 2015). "ERP29 works in the early secretory pathway in the ER, and overexpression of ERP29 resulted in higher expression of HSP27 in breast cancer cells." (PMID 24872842, 2014). "Fucoidan treatments resulted in down-regulation of the glucose regulated protein 78 (GRP78) in the metastatic MDA-MB-231 breast cancer cells, and of the ER protein 29 (ERp29) in the metastatic HCT116 colon cancer cells." (PMID 25232957, 2014). "For example, ERp29 which lacks the catalytic a-type domain has been shown to downregulate eLF2α which in turn upregulates Hsp27, resulting in the inhibition of apoptosis in breast cancer cells." (PMID 35965326, 2022). "In particular, they observed that ERp29 induced the overexpression of Hsp27 by downregulating the expression of eukaryotic translational initiation factor 2α (eIF2α), while the knockdown of Hsp27 in MDA-MB-231 breast cancer cells overexpressing ERp29, attenuated the doxorubicin resistance." (PMID 35453647, 2022). "Furthermore, ERP29 is a tumor suppressor gene via ERP29-MGMT (O6-methylguanine DNA-methyltransferase) axis to exert the function of radioresistant in MDA-MB-231 breast cancer cells." (PMID 31316127, 2019). "ERp29 induced EMT has been found in basal-like MDA-MB-231 breast cancer cells." (PMID 28874138, 2017). "Studies have shown that ERp29 may act as a tumor suppressor gene in breast cancer by regulating EMT process." (PMID 29108263, 2017). "ERp29 modulating EMT has been observed in breast cancer cells." (PMID 28874138, 2017).
breast carcinoma (continued). "Considering that ERp29 can drive MET in mesenchymal breast cancer cells, ERp29 may play an important role in promoting distant metastasis during disease progression in basal cell carcinoma." (PMID 27578920, 2016). "Targeting ERp29\MGMT axis may be useful for providing better treatment efficacy in combination with radiotherapy in breast cancer." (PMID 26420420, 2015). "In addition to ERp19, another member of PDI family, ERp29, has been previously studied in breast cancer and showed correlations to tumor cell growth and survival." (PMID 25940440, 2015). "In addition, endoplasmic reticulum protein 29 suppresses breast cancer cell invasion by upregulating numerous genes, including CDKN2B, indicating that CDKN2B is involved in cell invasion." (PMID 25202407, 2014). "In addition, overexpression of ERp29 may regulate ERK signalling in mesenchymal-like breast cancer cells, which in turn increases E-cadherin and further promotes cellular transition into epithelial properties." (PMID 35965326, 2022). "In breast cancer research, the results revealed that the expression of miR-205-5p was decreased in breast cancer tissues and miR-205-5p may inhibit gemcitabine resistance in breast cancer cells via inhibition of ERp29 expression." (PMID 33402116, 2021). "Overexpression of ERp29 may result in G0/G1 arrest and inhibit breast cancer cell proliferation." (PMID 24391750, 2013). "A recent study found that ERp29 could potentiate resistance to doxorubicin by up-regulating Hsp27 in breast cancer cells through sequently down-regulating the α subunit of the eukaryotic initiation factor 2 (elF2α), which can trigger apoptotic signals by activation of downstream molecule CHOP." (PMID 22160175, 2012).
viral infection (5 papers, 2006 to 2023). "Overall, this study establishes novel antiviral roles for ERp29 and Cx43 in restricting viral spread, suggesting their potential utility as pharmacological targets to minimize the deleterious effects of viral infection." (PMID 36572185, 2023). "As before, protein levels either increased or decreased upon IFN treatment, with all but one (Erp29) decreased during virus infection." (PMID 21774819, 2011). "In support of this, expression of the dominant-negative N terminal domain of ERp29 decreases Py infection, indicating ERp29 facilitates viral infection." (PMID 16603059, 2006). "Moreover, ERp29 facilitates viral infection via mediating membrane penetration." (PMID 20132541, 2010). "Specifically, ERp29 and other PDI family members were shown to facilitate the unfolding and ER retro-translocation of the polyomavirus VP1 protein, a key step in the virus infection cycle." (PMID 36572185, 2023). "Erp29 and Erp57 were increased upon IFN treatment, but significantly down-regulated during virus infection." (PMID 21774819, 2011).
colorectal cancer (4 papers, 2020 to 2023). A primary or metastatic malignant neoplasm that affects the colon or rectum. "Taken together, this study demonstrates a novel anti-cancer mechanism for CIL-102 to inhibit cell migration and the invasiveness of colorectal cancer cells via the upregulation of ERP29 and FUMH." (PMID 34572494, 2021). "In contrast, ERP29 downexpression was associated with decreased RT resistance in nasopharyngeal carcinoma cells, increased CDDP efficacy in lung cancer cell line with null p5317, and better prognosis of colorectal cancer patients." (PMID 33046743, 2020). "Here, we showed ERp29 is a novel target for microRNA-135a-5p (miR-135a-5p) to inhibit the progression of colorectal cancer (CRC); correspondingly, ERp29 acts as an oncoprotein in CRC by promoting proliferation and metastasis of CRC cells, and suppressing apoptosis of the cells." (PMID 34667160, 2021).
gastric cancer (4 papers, 2017 to 2020). A primary or metastatic malignant neoplasm involving the stomach. "Inhibition of EMT is accompanied by reduced invasive ability in gastric cancer cells with overexpression of ERp29." (PMID 30021604, 2018). "To investigate the expression of ERp29 in gastric cancer tissues, we first used immunohistochemical staining to evaluate the ERp29 protein levels in GC tissue microarray sections, which was obtained from a total of 75 individuals." (PMID 29108263, 2017). "The in vitro experiments indicated that over-expression of ERp29 in gastric cancer cells significantly suppressed the proliferation and migration of tumor cells, which is consistent with the result of the in vivo animal experiments." (PMID 29108263, 2017). "To further investigate the expression of ERp29 in gastric cancer cells, we used qRT-PCR and western blot analysis to examine ERp29 expression in gastric cancer cell lines and normal gastric mucosal epithelial cell line (GES-1)." (PMID 29108263, 2017). "In this study we used qRT-PCR and immuno-histochemical staining to detect the expression levels of ERp29 in gastric carcinoma." (PMID 29108263, 2017). "In this study, we used the lentivirus infection method to up-regulate ERp29 in two gastric carcinoma cell lines." (PMID 29108263, 2017). "In this study, we found that overexpression of ERp29 could increase the epithelial marker E-cadherin and decrease the mesenchymal cell markers N-cadherin and Vimentin, implying that ERp29 overexpression may suppress EMT in gastric cancer." (PMID 29108263, 2017). "In addition, Kaplan-Meier analysis showed that low expression of ERp29 was closely correlated to the short-term survival and prognosis of patients with gastric cancer." (PMID 29108263, 2017). "Thus, we conclude that ERp29 acts as a tumor suppressor gene in gastric cancer, and is expected to become a novel target of the treatment of GC." (PMID 29108263, 2017). "The results showed that ERp29 was located mainly in the cytoplasm of gastric carcinoma cells." (PMID 29108263, 2017). "Furthermore, our mechanistic investigations revealed that ERp29 reversed EMT process in gastric carcinoma, and its effect was related to the inactivation of ERK1/2 and AKT phosphorylation." (PMID 29108263, 2017). "Thus, we sought to determine whether ERp29 also participates in regulation of EMT process in the gastric cancer cells." (PMID 28874138, 2017). "Thus, we accept our hypothesis that ERp29 inhibits tumorigenicity by suppressing EMT in gastric cancer." (PMID 29108263, 2017). "However, the potential function of ERp29 in gastric cancer remains poorly understood." (PMID 29108263, 2017). "In conclusion, our studies indicate that ERp29 is down-regulated expression in gastric cancer tissues, and could inhibit GC cell proliferation and migration in vitro and in vivo." (PMID 29108263, 2017). "However, the expression and function of ERp29 in gastric cancer remain largely unknown." (PMID 29108263, 2017). "In this study, we found that the positive rate of ERp29 in gastric cancer tissues was significantly lower than that in adjacent non-tumor tissues." (PMID 29108263, 2017). "ERp29 expression was negatively correlated with TNM stage in GC tissues, suggesting that ERp29 may be involved in the metastasis of gastric cancer cells." (PMID 29108263, 2017). "To date, the biological function of ERp29 in gastric cancer has not been definitively reported." (PMID 29108263, 2017). "Among the 150 specimens, ERp29 staining was detected positive in 40 % (30 out of 75) of the gastric cancer compared with 88 % (66 out of 75) of adjacent non-tumor tissues, indicating that ERp29 expression in gastric carcinoma was lower than adjacent non-tumor tissues (***P<0.001)." (PMID 29108263, 2017). "In addition, we used qRT-PCR to detect the ERp29 mRNA levels in 38 pairs of gastric cancer tissues and adjacent non-tumor tissues." (PMID 29108263, 2017).
lung carcinoma (4 papers, 2017 to 2022). "ERp29 is highly expressed in numerous tumors and under the stress conditions, such as basal cell carcinoma and lung cancer progression and also cells exposed to radiation, sperm cells undergoing maturation." (PMID 29511484, 2017).
nasopharyngeal carcinoma (3 papers, 2012 to 2020). A carcinoma arising from the nasopharyngeal epithelium. "It was reported that ERp29 knockdown attenuated radioresistance and enhanced cell apoptosis in nasopharyngeal cancer cells." (PMID 26420420, 2015).
colon cancer (2 papers, 2014 to 2017). "In breast tumors and colon cancer, ERp29 expression associates with metastasis and prognostic risks of cancer." (PMID 29511484, 2017).
cystic fibrosis (2 papers, 2015 to 2020). Autosomal recessive disorder caused by pathogenic variants in the CFTR gene (cystic fibrosis transmembrane conductance regulator), which encodes a chloride and bicarbonate channel expressed in epithelial cells, and follow the diagnosis criteria. "Interestingly, A1AT contains a 188Y-I-F-F191 motif and preliminary data from our laboratory suggest ERp29 and A1AT may interact via this binding domain in co-precipitation experiments in Madin-Darby Canine Kidney (MDCK) and Cystic Fibrosis Bronchial Epithelial (CFBE41o-) cells (unpublished data)." (PMID 33013490, 2020).
gastric tumor (2 papers, 2017). "The lower expression of both ERp29 protein and mRNA level was also confirmed in the gastric tumor tissues as compared with the adjacent normal tissues by western blot analysis and qRT-PCR." (PMID 28874138, 2017).
insulinoma (2 papers, 2020 to 2024). "Therefore, we tested whether this ERp29/Sec24D interaction was also present and perhaps relevant in Min-6 insulinoma cells using a co-immunoprecipitation approach." (PMID 32433667, 2020). "Analogous experiments were performed in Ins-1 rat insulinoma cells, to confirm that the observed interactions were not species-specific, and revealed that ERp29 co-precipitates with (Pro)Insulin." (PMID 32433667, 2020).
prostate carcinoma (2 papers, 2022 to 2023). A carcinoma that arises from epithelial cells of the prostate gland.
age-related macular degeneration (1 paper, 2021). Age-related loss of vision in the central portion of the retina (macula), secondary to retinal degeneration. "Erp29 is an ER stress-responsive gene whose corresponding protein is considered neuroprotective; it has been shown to be down-regulated in the retina in human subjects with age-related macular degeneration." (PMID 33652836, 2021).
Alzheimer disease (1 paper, 2021). A progressive, neurodegenerative disease characterized by loss of function and death of nerve cells in several areas of the brain leading to loss of cognitive function such as memory and language. "ERp29 is involved in protein misfolding and mistrafficking, which are potent pathogenic features of PD and Alzheimer’s disease." (PMID 34946922, 2021).
astrocytoma (1 paper, 2023). "The current study extends our previous work by demonstrating that MHV-A59 infection of mouse primary astrocytes and mouse astrocytoma-derived DBT cells lead to increased ER stress and concomitant downregulation of the ER-resident Cx43 chaperone, ERp29." (PMID 36572185, 2023). "The mouse astrocytoma delayed brain tumor (DBT) cell line, which has been widely used in the MHV field to study the replication and propagation of different strains of the virus, was chosen as an immortalized cell line to further examine the effects of astrocyte MHV-A59 infection on ERp29 and Cx43." (PMID 36572185, 2023).
brain tumor (1 paper, 2023). "Critically, delayed brain tumor cells transfected to express exogenous ERp29 were less susceptible to MHV-A59 infection and showed increased Cx43-mediated GJIC." (PMID 36572185, 2023).
dementia (1 paper, 2021). Loss of intellectual abilities interfering with an individual's social and occupational functions. "Given that endoplasmic reticulum stress is related to Lewy body dementia, it is possible that ERp29 mutation also induces cortical neuronal damage and is linked to the progression of dementia in patients with PD." (PMID 34946922, 2021). "Few clinical studies have investigated the role of ZHX2 and ERP29 in PD or dementia." (PMID 34946922, 2021).
diabetes (1 paper, 2017). "Next, we examined the cellular expression of ERp29 and calreticulin, two major MAM-located chaperone proteins that are altered in diabetes." (PMID 28522876, 2017).
dysferlinopathy (1 paper, 2022). "There is a strong possibility that ERP29 is upregulated in dysferlinopathy as a compensatory mechanism." (PMID 36203997, 2022). "Consistent with the two datasets, MVP, GRN, and ERP29 expression were significantly upregulated, and RNF128, NFYB, and KPNA3 were significantly downregulated in the dysferlinopathy patients compared with the controls." (PMID 36203997, 2022). "In both datasets, MVP, GRN, and ERP29 showed significantly higher expression levels, while RNF128, NFYB, and KPNA3 had significantly lower expression levels in dysferlinopathy than normal controls." (PMID 36203997, 2022).
encephalitis (1 paper, 2023). An acute inflammatory process affecting the brain parenchyma. "While it has yet to be determined whether the activation of chaperones like ERp29 is the underlying mechanism of 4-PBA induced reduction of LACV in BCECs, this strategy represents a promising approach to combatting LACV-induced encephalitis." (PMID 37202395, 2023).